PANX1 (pannexin 1)
Diseases named in the same sentence as PANX1 in open-access papers (continued):
Sharing a sentence is not in itself a finding about the gene and the disease.
infection (23 papers, 2013 to 2025). The state of being infected such as from the introduction of a foreign agent such as serum, vaccine, antigenic substance or organism. "Panx1 has been implicated in inflammasome activation, neutrophil and dendritic cell regulation, and modulation of immune responses against infections, including SARS-CoV-2." (PMID 40978734, 2025). "Our data demonstrated that SARS-CoV-2 uses Pannexin-1 (Panx-1) channels to mediate infection and associated inflammation." (PMID 34841222, 2021). "Panx1 deficiency reduced CD8+ T cell proliferation and impaired their ability to control tumors and respond to infections." (PMID 40978734, 2025). "In vivo, CDI in mice confirms that in the colon C. difficile induces an increase in Panx1-3 days after infection and that its inhibition with a Panx1 inhibitor, both in vitro and in vivo, protects against apoptosis, while IL-6 expression remains unaffected." (PMID 40646589, 2025). "Taken together, these results demonstrate that tuft cells play a prominent role in local DC activation at the site of infection, which involves Trpm5 and Panx1 channels but is independent from ACh release from tuft cells." (PMID 39794305, 2025). "Moreover, bitter taste signaling in tuft cells as well as ATP release via Panx1 is crucial for infection outcome, since we observed a reduced survival in Trpm5−/− as well as Panx1−/− mice, when compared to Trpm5+/+ animals, and Trpm5−/− mice showed a greater weight loss 48 h post infection." (PMID 39794305, 2025). "Overall, we propose a protective influence of tuft cell-released ATP in bacterial infections, since Trpm5−/− and Panx1−/− mice demonstrated worse infection outcomes." (PMID 39794305, 2025). "The number of recruited DCs in Trpm5−/− as well as in Panx1−/− mice three days after infection was significantly lower compared to those in infected Trpm5+/+ mice." (PMID 39794305, 2025). "In contrast, Panx1 is upregulated under inflammatory conditions in microglia and astrocytes, which suggests that Panx1 hemichannels contribute to inflammatory responses in the case of injury or infection." (PMID 37371611, 2023). "After three days post-infection (p.i.), cecum and colon samples were collected to evaluate the expression of Panx1 by immunohistochemistry." (PMID 36072579, 2022). "Our data identified that Panx-1, a large ionic channel, mediates the release of ATP and inflammatory lipids by a mechanism of infection, but can be replication-independent." (PMID 35883688, 2022). "The analysis above suggests that, following 3V mediated activation, h-RBCs and t-RBCs both use pannexin-1 as the main conduit of 3V dependent ATP release, and that ATP efflux is enhanced as a consequence of infection." (PMID 24858837, 2014). "The addition of Probenecid (Prob) or mimetic Panx-1 peptide (10Panx) after entry, 12 h post-infection, to enable entry also resulted in reduced GFP production driven by reduced HIV entry and infection (representative images, GFP quantification, n=4, #p≤0.005 compared to HIV condition)." (PMID 40740680, 2025). "Finally, these genetic approaches cannot account for the influence of environmental factors such as inflammation due to injury or infection, which would be expected to have a major impact on PANX1 function and regulation, including neuronal PANX1." (PMID 37807670, 2023). "This review is intended to detail current topics related to HIV, including persistence within viral reservoirs, biomarkers of infection, and the newly identified host protein, Panx-1, and its function as a mediator of potential biomarkers of CNS damage in the current ART era." (PMID 35883688, 2022). "Moreover, bacterial and PAMP infection resulted in the release of ATP through Panx1 in tilapia and Japanese flounder." (PMID 35514966, 2022). "In addition to ATP, Panx1 has been demonstrated to release metabolites that play crucial roles in the resolution of inflammation and the maintenance of effector T cell populations post-infection." (PMID 40309905, 2025).
infection (continued). "Immunofluorescence analyses indicated that P2Y2 and the ATP-release channel pannexin-1 appeared to polarize to the virologic synapse; the latter is the interface between an infected donor cell and an uninfected target cell where cell-to-cell transfer and infection takes place." (PMID 26635799, 2015). "Thus, new potential ATP conduits might arise during infection, thereby altering the relative contribution of pannexin 1 to ATP release in infected RBCs." (PMID 24858837, 2014). "To examine the role of Panx-1 channel opening in viral replication, we used the cell line CEM-GFP cells, an HIV reporter cell line that, upon infection, induces GFP expression under the control of the HIV LTR." (PMID 40740680, 2025). "When the piglets were injected with probenecid or 25–100 mg/kg baicalin, the Panx-1, P2Y6 and P2X7 mRNA levels were decreased compared to those in the infection group (p < 0.01)." (PMID 39075542, 2024). "This prolonged opening of Panx-1, similar to the entry-mediated opening, is also required for HIV replication, as the pharmacological inhibition or knockdown of Panx-1 after the infection has been established abolishes HIV replication." (PMID 35883688, 2022). "The infection during gestation triggers the release of ATP from astrocytes via Cx43 and Panx1 unopposed channel, resulting in increased neuronal death mediated by P2X7 receptors and Panx1 channels." (PMID 29375373, 2017). "It has been reported that Panx-1 hemichannels, P2Y2 and Pyk2 are physically recruited to the infection synapse (the contact site between the viral and cellular membrane) in order to facilitate infection." (PMID 24672487, 2014). "Also, the use of a mimetic peptide (10Panx1) without any cytotoxic effect on the cells shows that targeting Panx-1 or downstream mediators of co-receptor clustering could potentially be a tool for blocking HIV entry, which could transition to blocking infection." (PMID 40740680, 2025). "Consistent with the infection results, some proteins (ARFP1, F120A, HTF4, NHEJ1, NUFP2, PANX1, and SP130) decreased in abundance but did not produce detectable cleavage products." (PMID 32997711, 2020).
neurological diseases (6 papers, 2012 to 2024). "Given that PANX1 is expressed in the earliest cell types of human development and is linked to neurological disease, we sought to explore PANX1 expression and localization throughout early stages of human brain development." (PMID 38212304, 2024). "We then performed enrichment analyses of the total neural PANX1 interactome to identify overrepresented biological pathways (e.g., relating to neurological diseases), including implicated PANX1-interacting proteins." (PMID 37807670, 2023). "Since PANX1 has been implicated to play a role in many pathological conditions including cardiovascular, inflammatory, and neurological diseases, identifying new PANX1 inhibitors may lead to the development of novel therapeutics targeting these PANX1-associated diseases." (PMID 38336804, 2024). "Interestingly, Panx1 and Cx43 are involved in mammalian neural inflammation, and multiple studies suggest that they could be targets for the treatment of neurological diseases in the future." (PMID 35514966, 2022). "Understanding the fundamental roles of Panx1 channels in NSC/NPCs is of critical importance given the vital roles that postnatal neurogenesis plays in normal brain health, as well in the progression of neurological diseases and the response to brain injury." (PMID 22458943, 2012).
bacterial infections (5 papers, 2022 to 2025). "In bacterial infections, PAMPs activate hemichannels formed by Cx43, Cx26, or Panx1, causing an outflow of ATP." (PMID 36699007, 2022). "Panx1 is also an important immune response gene involved in bacterial infection-induced ATP release in tilapia (Oreochromis niloticus)." (PMID 35514966, 2022). "Notably, Panx1 not only plays a role in the early stage of acute bacterial infections but also participates in the long-term immune surveillance mechanism of the liver." (PMID 41376789, 2025). "In fish, Panx1, Cx32, and Cx43 were upregulated by PAMPs stimulation or bacterial infection." (PMID 35514966, 2022).
cardiovascular diseases (5 papers, 2023 to 2026). "In the context of cardiovascular diseases, Panx1 has also been identified as a key mediator in inflammatory processes associated with endothelial damage." (PMID 40978734, 2025). "However, more research is required to establish a clear benefit of probenecid treatment and the subsequent Panx1 inhibition in human cardiovascular disease." (PMID 41569301, 2026). "These trials highlight the growing evidence supporting the utilization of probenecid in the treatment of cardiovascular disease, which could link to important cardiac functions for Panx1." (PMID 41569301, 2026). "Aside from Panx1 targeting peptides which have yet to reach clinical success, evidence suggests that Probenecid and Spironolactone are the most selective of the pharmacologic pannexin inhibitors, and their therapeutic role in cardiovascular disease is a topic of ongoing research." (PMID 41569301, 2026).
inflammation (4 papers, 2023 to 2025). Aberrant reaction of the microcirculation characterized by movement of fluid and leukocytes from the blood into extravascular tissues. "For example, vascular inflammation caused by platelet-derived microvesicles can be explained by the action of extracellular ATP released through Panx1 channels, as these microvesicles contain a large amount of LPCs." (PMID 40309905, 2025). "In a model of dust mite-induced inflammation, Panx1 deficiency exacerbated pulmonary inflammation, while its reexpression in T cells reduced pathology." (PMID 40978734, 2025). "HG-9-91-01 administration blocked Panx1 activation in vitro, and Panx1 S205A mutant mice displayed increased lung inflammation in a house-dust mite model of allergic airway inflammation, mirroring the phenotype of Panx1 KO animals." (PMID 36731029, 2023). "Additionally, in chronic vascular inflammation, Panx1 regulates leukocyte trafficking and endothelial cell activation, making it a viable pharmacological target for mitigating persistent inflammatory pathologies." (PMID 40978734, 2025).
neurodegenerative disease (4 papers, 2021 to 2025). A disorder of the central nervous system characterized by gradual and progressive loss of neural tissue and neurologic function. "Overall, the two neurodevelopmental disorder susceptibility gene sets exhibited a relatively larger degree of overlap with the PANX1 interactome than did the neurodegenerative disease susceptibility gene sets." (PMID 37807670, 2023). "To this end, we explored connections between synaptic neurodevelopmental disorder and neurodegenerative disease susceptibility genes discovered by genome-wide association studies (GWASs), and the neural PANX1 interactome (483 proteins) identified from mouse Neuro2a (N2a) cells." (PMID 37807670, 2023). "Pharmacological inhibition of Panx1 has shown therapeutic benefits in preclinical models of inflammatory, cardiovascular, and neurodegenerative diseases, establishing it as a promising and versatile therapeutic target." (PMID 40978734, 2025). "In neurodegenerative diseases such as stroke and hepatic encephalopathy, Panx1 inhibition has shown promising results in mitigating neuronal damage and improving cognitive function." (PMID 40978734, 2025). "Pannexin 1 (Panx 1) is a membrane channel that mediates substance release in many neurodegenerative diseases." (PMID 34475813, 2021). "To date, and according to the literature reviewed in this manuscript, Panx1 inhibitors and modulators have demonstrated considerable therapeutic potential in numerous preclinical models of inflammatory, autoimmune, cardiovascular, and neurodegenerative diseases." (PMID 40978734, 2025).
brain disease (3 papers, 2022 to 2024). "On the other hand, mounting evidence has documented that Cx43 hemichannels and Panx1 channels disturb astrocytic function in multiple brain diseases and pathological conditions." (PMID 38576018, 2024). "Thus, the functional interaction between Panx1 channels and Rho GTPases could be of pivotal relevance considering that numerous brain disorders such as neuropsychiatric and neurodegenerative conditions are manifested with abnormalities in the neuronal actin cytoskeleton." (PMID 36429074, 2022).
lung (3 papers, 2020 to 2024). "Moreover, their results demonstrate a novel role of endothelial Panx1 channels in the regulation of vascular inflammation after lung IR: when blocking Panx1-mediated ATP release by Panx1 inhibitors, lung IR injury could be attenuated." (PMID 33391010, 2020).
cardiac disease (2 papers, 2020 to 2026). "Panx1 is critical in the response to cardiac disease conditions such as I/R injury and hypertrophy, predominantly through its involvement in purinergic signaling." (PMID 41569301, 2026). "It is therefore challenging to explore HCs and Panx1 channel function in inflammation and oxidative stress which precede or accompany heart disease." (PMID 33383853, 2020). "ATP released to the vasculature through HCs and Panx1 channels provides the driving stimulus for early inflammatory response to implanted devices in heart disease." (PMID 33383853, 2020). "All these events during heart disease development can activate both HCs and Panx1 channels and promote arrhythmias through bi-directional ion passage and small metabolic or signaling molecules below 1–2 kDa." (PMID 33383853, 2020). "Data on mitochondrial HCs and Panx1 channel implication in heart disease, heart failure and malignant arrhythmias is lacking, and this invites challenging research." (PMID 33383853, 2020).
neurodevelopmental disorder (2 papers, 2020 to 2023). A behavioral and cognitive disorder with onset during the developmental period that involves impaired or aberrant development of intellectual, motor, or social functions. "Overall, the two investigated neurodevelopmental disorders exhibited the largest overlap in synaptic susceptibility genes and were more abundantly represented in the PANX1 interactome." (PMID 37807670, 2023). "PANX1 is also linked to neurodevelopmental disorders indirectly through its interacting partner CRMP2 and its downstream signaling effectors and interactors, purinergic receptors." (PMID 32737184, 2020).
infectious disease (1 paper, 2022). A disorder directly resulting from the presence and activity of a microbial, viral, or parasitic agent in humans. "Though current knowledge of the mechanisms underlying the activity of lopinavir and favipiravir cannot be traced back to NLRP3 inflammasome activation, these drugs can be linked to certain infectious diseases in which Panx1 channels are involved." (PMID 35628472, 2022). "Due to similar links to inflammation, NLRP3 inflammasome activation, and Panx1-related infectious diseases, the proposed group of drugs could hold great potential to uncover additional Panx1 channel inhibitors." (PMID 35628472, 2022).
metabolic disorders (1 paper, 2024). "Restoration of hepatic PANX1 rescued the metabolic disorders of PANX1-deficient mice (P < 0.05)." (PMID 38937853, 2024). "As previously determined, the upregulation of hepatic PANX1 serves as a compensatory mechanism against metabolic disorders." (PMID 38937853, 2024).
PANX1 also shares sentences with these, for which no sentence is quoted: pancreatic cancer (4 papers); esophageal cancer (3); migraine aura (3); atrial fibrillation (2); basal cell carcinoma (2); Duchenne muscular dystrophy (2); endometrial carcinoma (2); experimental autoimmune encephalomyelitis (2); fibrosis (2); lymphoma (2); metastatic melanoma (2); Seizure (2); acute myocardial infarction (1); adenocarcinoma (1); allergic asthma (1); amyotrophic lateral sclerosis (1); Atrophy (1); autosomal dominant polycystic kidney disease (1); brain tumors (1); cervical cancer (1); cervical squamous cell carcinoma (1); channelopathy (1); chlamydial infections (1); chronic liver failure (1); colon adenocarcinoma (1); developmental and epileptic encephalopathy (1); diabetic cardiomyopathy (1); endocervical adenocarcinoma (1); Focal cortical dysplasia (1); head and neck cancer (1).
A further 44 diseases each share a sentence with PANX1 in 1 paper.